ITSN1 (intersectin 1)
Description:
Adapter protein that provides a link between the endocytic membrane traffic and the actin assembly machinery. Acts as a guanine nucleotide exchange factor (GEF) for CDC42, and thereby stimulates actin nucleation mediated by WASL and the ARP2/3 complex. Plays a role in the assembly and maturation of clathrin-coated vesicles (By similarity). Recruits FCHSD2 to clathrin-coated pits. Involved in endocytosis of activated EGFR, and probably also other growth factor receptors (By similarity). Involved in endocytosis of integrin beta-1 (ITGB1) and transferrin receptor (TFR); internalization of ITGB1 as DAB2-dependent cargo but not TFR may involve association with DAB2. Promotes ubiquitination and subsequent degradation of EGFR, and thereby contributes to the down-regulation of EGFR-dependent signaling pathways. In chromaffin cells, required for normal exocytosis of catecholamines. Required for rapid replenishment of release-ready synaptic vesicles at presynaptic active zones (By similarity). Inhibits ARHGAP31 activity toward RAC1. [Isoform 1]: Plays a role in synaptic vesicle endocytosis in brain neurons.
Synonyms: ITSN; SH3D1A; SH3P17; MGC134948; MGC134949
Tractability: Small molecule: a structure with a bound ligand is known; it has a binding pocket of medium quality. Antibody: UniProt places it where antibodies can reach, with high confidence; its Gene Ontology location is reachable by antibodies, with high confidence; the Human Protein Atlas places it where antibodies can reach. PROTAC: ubiquitination databases record sites on it; its protein half-life has been measured.
Gene: Protein-coding gene on chromosome 21 (33,642,400 to 33,899,861, forward strand). Ensembl gene ENSG00000205726.
Subcellular location: Endomembrane system; Synapse, synaptosome; Cell projection, lamellipodium; Cell membrane; Membrane, clathrin-coated pit; Recycling endosome; Endosome; Cytoplasmic vesicle; Cytoplasm (Isoform 2); Nucleus envelope; Endomembrane system (Isoform 5)
Subcellular location (Human Protein Atlas): Plasma membrane; Nucleoplasm
Pathways (Reactome):
Signal Transduction: CDC42 GTPase cycle; G alpha (12/13) signalling events; NRAGE signals death through JNK; RHOG GTPase cycle; RHOQ GTPase cycle
Vesicle-mediated transport: Cargo recognition for clathrin-mediated endocytosis; Clathrin-mediated endocytosis
Developmental Biology: EPHB-mediated forward signaling
Gene Ontology:
Molecular function: molecular adaptor activity; proline-rich region binding; protein binding; calcium ion binding; guanyl-nucleotide exchange factor activity; protein-macromolecule adaptor activity; kinase activator activity
Biological process: intracellular protein localization; clathrin-dependent synaptic vesicle endocytosis; regulation of small GTPase mediated signal transduction; intracellular signal transduction; positive regulation of caveolin-mediated endocytosis; positive regulation of dendritic spine development; positive regulation of growth hormone secretion; regulation of cell communication; regulation of modification of postsynaptic actin cytoskeleton; regulation of postsynapse organization; regulation of signaling; synaptic vesicle endocytosis
Cellular component: clathrin-coated pit; cytoplasm; endomembrane system; nuclear envelope; nucleoplasm; plasma membrane; recycling endosome; cytoplasmic vesicle; cytosol; endosome; intracellular vesicle; apical dendrite; calyx of Held; dendritic spine; endocytic vesicle; glutamatergic synapse; lamellipodium; neuronal cell body; postsynaptic actin cytoskeleton; postsynaptic endocytic zone; presynaptic endocytic zone; synapse
Genetic constraint (gnomAD): Loss-of-function variants: 44 observed, 185.99 expected, observed/expected ratio (o/e) 0.24, 90% interval 0.19 to 0.3. The upper end of that interval is the gene's LOEUF score, 0.3, which puts it in group 1 of 6, group 1 being the genes least tolerant of losing a copy. Missense variants: 1,318 observed, 1,844.9 expected, observed/expected ratio (o/e) 0.71, 90% interval 0.68 to 0.75. Synonymous variants: 666 observed, 695.94 expected, observed/expected ratio (o/e) 0.96, 90% interval 0.9 to 1.02.
Homologues: Orthologues: chimpanzee ITSN1 (99% identical), macaque ITSN1 (99% identical), rabbit ITSN1 (98% identical), dog ITSN1 (97% identical), mouse Itsn1 (95% identical), rat Itsn1 (94% identical), guinea pig ITSN1 (91% identical), tropical clawed frog itsn1 (86% identical), pig ITSN1 (82% identical), zebrafish itsn1 (78% identical), Caenorhabditis elegans itsn-1 (19% identical), Drosophila melanogaster Dap160 (13% identical), and 2 more. Paralogues in human: ITSN2 (60% identical), EPS15L1 (12% identical), EPS15 (12% identical), EHD1 (7% identical), REPS1 (7% identical), REPS2 (7% identical), EHD4 (7% identical), EHD2 (6% identical), EHD3 (6% identical), SRL (4% identical).
Diseases named in the same sentence as ITSN1 in open-access papers:
ITSN1 is named in the same sentence as 67 diseases in open-access papers, as found by Europe PMC text mining. Sharing a sentence is not in itself a finding about the gene and the disease. The quoted sentences say what the papers report.
Down syndrome (14 papers, 2013 to 2025). "Itsn1 overexpression in humans is associated with Down syndrome, while Itsn1 mutation in mice produces a learning and memory deficit, probably due to a loss of interhemispheric connections." (PMID 39383250, 2025). "ITSN1 has been implicated in Down’s syndrome and AD, possibly via c-JUN N terminal kinase activation." (PMID 27466139, 2016). "While this is the first study to report the differential expression of ITSN2 in replicative senescence, a recent report had implicated dysregution and overexpression of ITSN1 in Down Syndrome patients in an age-associated manner." (PMID 23472054, 2013). "As previously reported, ITSN1 could predict neurodegenerative diseases early, such as AD and Down syndrome." (PMID 32655392, 2020). "How dysregulation of ITSN1 expression may contribute to the neural phenotypes characteristic of Down syndrome remains elusive but studies such as ours take us a step further along the pathway of unraveling the molecular mechanisms responsible." (PMID 32161523, 2020). "We may speculate that perturbations in the expression levels of ITSN1 might contribute to the development of Alzheimer’s disease-like neuropathology and cognitive deficits in Down syndrome." (PMID 32161523, 2020). "Dysregulation of endocytosis in Down syndrome has been linked to an increased dose of several endosomal pathway-related genes that map to chromosome 21, such as amyloid precursor protein (APP), synaptojanin-1 (SYNJ1), intersectin-1 (ITSN1), and regulator of calcineurin 1 (RCAN1)." (PMID 38540156, 2024). "As age is the highest risk factor for AD, CME proteins increase with age, and ITSN1 itself is increased with age in as shown in a Down Syndrome (DS) mouse model, there is a high likelihood that age-related changes may play an important role in ITSN1 function and dysfunction in AD." (PMID 38915309, 2024). "Another adaptor/scaffold protein, intersectin 1 (ITSN1) has been shown to be deregulated in AD and Down syndrome (DS) patients, as well as in several cancers." (PMID 33240194, 2020). "Two genes involved in endocytosis, both located on chromosome 21, are intersectin-1 (ITSN1) and the regulator of calcineurin-1 (RCAN1, formerly called Down syndrome candidate region 1)." (PMID 31263630, 2019). "Intersectin-1 (ITSN1), a scaffold protein associated with Down syndrome, physically interacts with Dab1 and VLDLR but not ApoER2." (PMID 32604886, 2020).
Alzheimer disease (8 papers, 2013 to 2025). A progressive, neurodegenerative disease characterized by loss of function and death of nerve cells in several areas of the brain leading to loss of cognitive function such as memory and language. "Recently, ITSN1 was suggested to contribute to Alzheimer’s disease and to the aggregation of huntingtin during Huntington’s disease." (PMID 23936226, 2013). "Over-expressed Itsn1 and amyloid beta (A4) precursor protein (App) may contribute to the early development of Alzheimer’s disease in DS individuals by accelerating beta amyloid and neurofibrillary tangle accumulation via increased endocytosis activity in neurons." (PMID 25052193, 2014). "Thus genes such as RUNX1 (which may contribute to childhood leukaemia in people with DS), APP (a key Alzheimer disease gene) and SYNJ1, RCAN1 and ITSN1, which have been linked to endosomal/synaptic abnormalities are unlikely to contribute to the phenotype of this mouse model of DS." (PMID 23596509, 2013). "Although the relationship between ITSN1 and PPM1A and aging has not yet been explored, diseases related to it, such as Alzheimer’s disease, usually occur along with aging, which may indicate that ITSN1 and PPM1A has a certain correlation with aging." (PMID 38926642, 2024).
neuroblastoma (7 papers, 2013 to 2024). Neuroblastoma (NB) is the most common solid, extracranial childhood tumor. "In support of this notion is a study that showed depletion of ITSN1 in EGF-stimulated neuroblastoma cells resulted in a 50% reduction in the activation of AKT." (PMID 32161523, 2020). "Even though low expression of ITSN1 was recently correlated with higher grade in breast and lung cancer, A role for ITSN in neuroblastoma has been shown by a study where knockdown of ITSN decreased orthotopic neuroblastoma growth in mice." (PMID 32322580, 2020). "Russo and O’Bryan demonstrated that ITSN1 is highly expressed in primary neuroblastoma (NB) tumors and tumor cell lines." (PMID 23574942, 2013). "Meanwhile, silencing ITSN1 expression decreased anchorage-independent growth in neuroblastoma." (PMID 34625530, 2021). "Intersectin 1 (ITSN1) has the transforming potential and is shown to be involved in the tumorigenesis of neuroblastoma." (PMID 32992741, 2020). "Overexpression of ITSN1 leads to anchorage-independent growth and tumorigenesis in neuroblastoma and proliferation of glioblastoma cells through Raf/MEK/ERK pathway activation, demonstrating an essential role of ITSN1 in the development of malignancy and tumor progression." (PMID 33240194, 2020).
Sepsis (7 papers, 2019 to 2025). Sepsis is defined as life-threatening organ dysfunction caused by a dysregulated host response to infection. "Long non-coding RNA intersectin 1-2 (lnc-ITSN1-2) is associated with inflammation, multiple organ dysfunction, and an increased risk of mortality in patients with sepsis." (PMID 40867920, 2025). "Circulating lncRNA ITSN1‐2 is upregulated, and its high expression associates with increased disease severity and inflammation as well as poor prognosis in sepsis patients." (PMID 30803045, 2019). "Summarily, circulating lncRNA ITSN1‐2 is upregulated and its high expression associates with increased disease severity and inflammation as well as poor prognosis in sepsis patients." (PMID 30803045, 2019). "Besides, prior research illustrates that lnc‐ITSN1‐2 is linked with aggravated inflammation in sepsis patients." (PMID 35243686, 2022). "In conclusion, lnc‐ITSN1‐2 is highly expressed and correlates with inflammation, multiple organ dysfunction, and mortality risk in sepsis patients, indicating lnc‐ITSN1‐2 may serve as a potential biomarker in sepsis patients." (PMID 35243686, 2022). "Hence, the study aimed to explore the relationship of lnc‐ITSN1‐2 with Th cells, inflammation, disease severity, multiple organ dysfunction, and mortality risk in sepsis." (PMID 35243686, 2022). "The current study was cross‐sectional research, which revealed that lnc‐ITSN1‐2 might be a potential biomarker of sepsis, while the causality between sepsis and lnc‐ITSN1‐2 was hard to explore." (PMID 35243686, 2022). "Given that sepsis arises from dysregulated inflammatory response to infection, even more severe than RA, we hypothesized that lncRNA ITSN1‐2 might have diagnostic value in sepsis." (PMID 30803045, 2019). "In sepsis patients, lnc‐ITSN1‐2 related to primary infection sites (Χ2/Z = 8.384, p = 0.039); among these, the lnc‐ITSN1‐2 was highest in patients with other infections and lowest in patients with abdominal infection." (PMID 35243686, 2022). "In our study, lnc‐ITSN1‐2 was associated with elevated Th17 cells, inflammation, and APACHE II score in sepsis patients." (PMID 35243686, 2022). "In the current study, we aimed to evaluate the relationship of lnc‐ITSN1‐2 with Th1 cells, Th17 cells, inflammation, multiple organ injury, and 28‐day mortality in sepsis patients." (PMID 35243686, 2022). "Peripheral blood mononuclear cells (PBMC) were isolated from 95 sepsis patients and 50 health controls, followed by lnc‐ITSN1‐2 evaluation using RT‐qPCR." (PMID 35243686, 2022). "In the present study, we evaluated the relationship of lnc‐ITSN1‐2 with prognosis in sepsis patients, which illustrated that lnc‐ITSN1‐2 presented an increasing trend in deaths." (PMID 35243686, 2022). "High levels of ITSN1‐2 were correlated with elevated disease severity, inflammation, and poor prognosis in sepsis patients." (PMID 34956235, 2021). "The lncRNA ITSN1‐2 expression was higher in sepsis patients compared to healthy controls (P < 0.001)." (PMID 30803045, 2019). "In line with these previous studies, we discovered that high expression of lncRNA ITSN1‐2 was associated with increased APACHE II score, CRP, TNF‐α, IL‐6, and IL‐8 levels in sepsis patients." (PMID 30803045, 2019). "Multiple studies have demonstrated that elevated expression of lncRNA ITSN1-2 in peripheral blood is significantly positively correlated with inflammatory responses and poor prognosis in various diseases, including sepsis, acute ischemic stroke, ankylosing spondylitis, and acute pancreatitis." (PMID 40629453, 2025). "Lnc‐ITSN1‐2 reflects sepsis progression and unfavorable prognosis to some extent, which may serve as a potential biomarker to improve the management of sepsis patients." (PMID 35243686, 2022). "The findings of this study indicates that lnc‐ITSN1‐2 reflects sepsis progression and unfavorable prognosis to some extent, which may serve as a potential biomarker to improve the management of sepsis patients." (PMID 35243686, 2022).
Sepsis (continued). "However, the relationship between lnc‐ITSN1‐2 and disease severity in sepsis is not fully understood." (PMID 35243686, 2022). "Our results displayed lnc‐ITSN1‐2 was upregulated in sepsis patients." (PMID 35243686, 2022). "Lnc‐ITSN1‐2 in sepsis patients was higher than it in health controls (Z = −7.328, p < 0.001)." (PMID 35243686, 2022). "Besides, lnc‐ITSN1‐2 positively associated with total SOFA score (rs = 0.295, p = 0.022) in sepsis patients." (PMID 35243686, 2022). "Lnc‐ITSN1‐2 in sepsis was more increased than it in health controls (Z = −7.328, p < 0.001)." (PMID 35243686, 2022). "The ROC curve disclosed that lncRNA ITSN1‐2 expression could distinguish sepsis patients from healthy controls with area under the curve (AUC) 0.777 (95% confidence interval (CI): 0.740‐0.813)." (PMID 30803045, 2019). "lncRNA ITSN1‐2 was highly expressed in sepsis patients compared to healthy controls and could differentiate sepsis patients from healthy controls with area under the curve (AUC) 0.777 (95% CI: 0.740‐0.813)." (PMID 30803045, 2019). "Besides, our study presented the relationship between lnc‐ITSN1‐2 and multiple organ dysfunction in sepsis patients, which showed that the lnc‐ITSN1‐2 related to raised SOFA score; moreover, it was positively associated with respiratory system, cardiovascular system, and renal system injury." (PMID 35243686, 2022). "Thus, our research invited 95 sepsis patients and 50 health controls to compare lnc‐ITSN1‐2." (PMID 35243686, 2022). "However, the linkage of lnc‐ITSN1‐2 with Th cells and multiple organ dysfunction in sepsis patients remains unknown, which needs to be further explored." (PMID 35243686, 2022). "However, the role of lnc‐ITSN1‐2 in sepsis needs to be further explored." (PMID 35243686, 2022). "In addition, lncRNA ITSN1‐2 was highly expressed in non‐survivors compared to survivors and could distinguish survivors from non‐survivors in sepsis patients with AUC 0.654 (95% CI: 0.581‐0.726)." (PMID 30803045, 2019). "Thus, the objective of this study was to assess whether lncRNA ITSN1‐2 could distinguish sepsis from healthy controls, and its correlation with disease severity, inflammation, and survival in sepsis patients." (PMID 30803045, 2019). "Lnc‐ITSN1‐2 had a positive connection with CRP (rs = 0.338, p = 0.001) and APACHE II score (rs = 0.231, p = 0.024) in sepsis patients." (PMID 35243686, 2022). "Lnc‐ITSN1‐2 correlated with increased interferon‐gamma (p = 0.009), Th17 cells (p = 0.022), and interleukin‐17A (p = 0.006), but not Th1 cells (p = 0.169) in sepsis patients." (PMID 35243686, 2022). "In view of lnc‐ITSN1‐2, although there are three previous studies elucidating the potential of lnc‐ITSN1‐2 for the disease risk of inflammation‐related diseases (including RA, sepsis, and CAD), no previous study has been carried out to explore the role of lnc‐ITSN1‐2 in AIS until now." (PMID 31647141, 2020).
glioma (6 papers, 2019 to 2025). A benign or malignant brain and spinal cord tumor that arises from glial cells (astrocytes, oligodendrocytes, ependymal cells). "Specifically, the short variant of ITSN1 promoted the development of glioma, whereas the long variant exerted a tumor-suppressive effect." (PMID 35832652, 2022). "These interactions regulate cellular signaling pathways essential for vesicular trafficking, suggesting a critical role of ITSN1 in glioma progression." (PMID 39915450, 2025). "While ITSN1-s was positively correlated with malignancy of glioma, the ITSN1-l exerted an opposite influence." (PMID 39915450, 2025). "One gene of particular interest is ITSN1 (intersectin 1), which undergoes differential splicing and is currently being investigated for its role in glioma genesis." (PMID 39915450, 2025). "Our work along with our previous studies provided solid evidence that two major isoforms of ITSN1 regulated by alternative splicing displayed opposite roles in glioma progression." (PMID 36171198, 2022). "Taken together, we concluded that PTBP1 promoted glioma progression by regulating alternative splicing of ITSN1." (PMID 36171198, 2022). "Further, our studies revealed that PTBP1 promoted glioma progression by regulating alternative splicing of ITSN1, which further confirmed the important function of alternative splicing in cancer." (PMID 36171198, 2022). "The efforts to discover the mechanisms of ITSN1 isoform-specific function will provide novel insights to detect more effective therapeutic strategies for glioma treatment." (PMID 31160551, 2019). "In the present study, we first demonstrated the existence of ITSN1 alternative splicing in glioma progression of TCGA dataset." (PMID 31160551, 2019). "Indeed, this RNA-binding protein (RBP) targeted a sequence on the exon 30 of ITSN1, promoting its inclusion and leading thus to an increased ratio of ITSN1-s/ITSN1-l which further promotes the proliferation and motility of glioma." (PMID 39915450, 2025). "Finally, we summarized a proposed schema that PTBP1 enhanced the inclusion of ITSN1 exon 30 to promote glioma progression." (PMID 36171198, 2022). "Analysis of TCGA database identified the mRNA expression of two isoforms of ITSN1 in glioma." (PMID 31160551, 2019). "At present, the opposite function of ITSN1 two isoforms was only studied in the progression of glioma; whether it is similar or not in other tumors needs to be verified." (PMID 31160551, 2019).